BROX (BRO1 domain and CAAX motif containing)
Description:
Nuclear envelope-associated factor that is involved in the nuclear envelope ruptures during interphase (NERDI) repair, where it is locally recruited by CHMP5 and reduces cytoskeletal stress through its action on SYN2 to help reseal the ruptured membrane.
Synonyms: C1orf58; FLJ32421
Tractability: Small molecule: it has a binding pocket of medium quality. PROTAC: ubiquitination databases record sites on it; its protein half-life has been measured.
Gene: Protein-coding gene on chromosome 1 (222,711,691 to 222,735,196, forward strand). Ensembl gene ENSG00000162819.
Subcellular location: Nucleus membrane
Subcellular location (Human Protein Atlas): Golgi apparatus; Cytosol; Nucleoplasm
Gene Ontology:
Molecular function: protein binding
Biological process: mitotic nuclear membrane reassembly
Cellular component: extracellular exosome; nuclear envelope; nuclear membrane
Genetic constraint (gnomAD): Loss-of-function variants: 19 observed, 24.82 expected, observed/expected ratio (o/e) 0.77, 90% interval 0.53 to 1.12. The upper end of that interval is the gene's LOEUF score, 1.12, which puts it in group 4 of 6, group 1 being the genes least tolerant of losing a copy. Missense variants: 234 observed, 247.57 expected, observed/expected ratio (o/e) 0.95, 90% interval 0.85 to 1.05. Synonymous variants: 80 observed, 86.7 expected, observed/expected ratio (o/e) 0.92, 90% interval 0.77 to 1.11.
Homologues: Orthologues: chimpanzee BROX (99% identical), macaque BROX (99% identical), rabbit BROX (96% identical), dog BROX (95% identical), pig BROX (94% identical), guinea pig BROX (93% identical), rat Brox (92% identical), mouse Brox (92% identical), tropical clawed frog brox (79% identical), zebrafish brox (74% identical), Caenorhabditis elegans B0507.2 (40% identical).
Diseases named in the same sentence as BROX in open-access papers:
BROX is named in the same sentence as 4 diseases in open-access papers, as found by Europe PMC text mining. Sharing a sentence is not in itself a finding about the gene and the disease. The quoted sentences say what the papers report.
bladder cancer (2 papers, 2017 to 2023). "These included proteins previously associated with bladder cancer and also additional novel such as PGRMC1, FUCA1, BROX and PSMD12, which were further confirmed by immunohistochemistry." (PMID 29050215, 2017).
cancer (2 papers, 2017 to 2026). A tumor composed of atypical neoplastic, often pleomorphic cells that invade other tissues. "Alternative splicing was pervasive, with recurrent high-magnitude events at cancer-relevant loci including GJA1 (SE), NF2 (A3/A5), LIN37 (A5), ECT2 (A3/A5), BCL2L11 (A3), UQCRH (A5), CSE1L (A3), BROX (A3), and multiple ZNFs." (PMID 41952686, 2026).
tumor (2 papers, 2021 to 2023). "Intriguingly, haploinsufficiency of BROX is associated with familial non-medullary thyroid cancer; thus, it is conceivable that NE instability associated with BROX deficiencies may contribute to tumor cell invasion." (PMID 34818527, 2021).
BROX also shares sentences with these, for which no sentence is quoted: viral infections (1 paper).